PTX3 (pentraxin 3)
Diseases named in the same sentence as PTX3 in open-access papers (continued):
Sharing a sentence is not in itself a finding about the gene and the disease.
tumor (continued). "Recently, the PTX3-derived small molecule NSC12 has been identified as the first orally active pan-FGF trap able to inhibit FGFR activation and tumor growth in various FGF-dependent murine and human tumor models." (PMID 31487962, 2019). "As observed for different FGF-dependent tumor cell types, this activates an autocrine loop of stimulation in B16-LS9 cells, which is inhibited by the overexpression of the natural extracellular FGF trap PTX3." (PMID 31487962, 2019). "PTX3 accumulation in tumor stroma and bloodstream obtained through endothelial specific overexpression of PTX3 in transgenic mice, affects tumorigenic, angiogenic, and metastatic potential of various syngeneic FGF-dependent tumor cell lines." (PMID 31533326, 2019). "Of note, in keeping with the lack of pathological consequences following constitutive PTX3 overexpression in transgenic mice, the anti-tumor action of NSC12 occurs in the absence of any significant effect on body weight and survival of treated animals." (PMID 31487962, 2019). "Accordingly, the average weight of harvested PTX3-overexpressing MC17-51 and HT-1080 tumors was significantly reduced when compared to mock derived lesions and was also accompanied by a reduction in pHH3+ proliferating cells and of CD31+ tumor vessels." (PMID 30443492, 2018). "As a consequence of the anti-FGF2/anti-angiogenic activity of PTX3, FGF2-dependent syngeneic tumor grafts of different origin were characterized by impaired FGFR1 activation and reduced CD31+ vascularization and tumor growth when injected in TgN(Tie2-hPTX3) mice." (PMID 30349543, 2018). "The enhancement of binding between tumor and endothelial cells was observed in oleate-treated parental but not PTX3-depleted cells." (PMID 28489600, 2017). "PTX3 and RELA were negatively correlated with tumor volume in our cohort." (PMID 28327132, 2017). "For the first time, we found that tumor-derived PTX3 promoted HNSCC metastasis but not tumor cell growth." (PMID 28489600, 2017). "In this context, it is important to acknowledge that higher PTX3 and CXCL8 blood levels in patients with recurrence of disease in this study represent a mere phenomenological evidence of the inflammatory reaction at the tumor site." (PMID 26859579, 2016). "With VEGF tumor overexpression, IGFBP-3, PTX-3, and TIMP-4 increased significantly in the plasma." (PMID 27995973, 2016). "The TIF secretome was, for the most part, distinctly different from the plasma secretome, although some factors such as TIMP-1, IGFBP-1, PTX3, uPA and IGFBP-3 were observed in both TIF and plasma and may provide plasma biomarkers of the tumor secretome." (PMID 27995973, 2016). "Compared to the 10 proteins (GM-CSF, IGFBP-1, IGFBP-3, PTX-3, PDGF-AA, serpin E1, PEDF, TIMP-1, TIMP-4 and uPA) detected in the plasma of MDA-MD-231_WT tumor bearing mice, only 2 (serpin E1 and TIMP-1) were detected in the plasma of MCF-7_WT tumor bearing mice." (PMID 27995973, 2016). "Since PTX3 had no direct effects on tumor cell growth, attention was focused on cancer-related inflammation (CRI)." (PMID 26075183, 2015). "Although hepatocytes are not considered a primary source of PTX3, studies have demonstrated that PTX3 can promote the proliferation of HCC cells and induce epithelial–mesenchymal transition a process closely linked to tumor cell invasion and metastasis." (PMID 41462970, 2025). "PTX3 is a component of the innate immune response that is produced at inflammatory sites, and elevated tissue PTX3 expression in tumor tissue does not necessarily translate into increased plasma concentrations, as circulating levels depend on both local secretion dynamics and systemic clearance." (PMID 41373493, 2025). "Alternatively, the sustained elevation of serum PTX3 could be due to circulating tumor cells that have not been entirely eliminated by either chemotherapy or the immune system." (PMID 39686456, 2024).
tumor (continued). "Subsequently, we evaluated whether the blockade of Ptx3 with WHC-001 can also attenuate MC38 tumor growth when MEFs were not coinjected." (PMID 38243273, 2024). "One theory suggests that PTX3 overexpressed by tumors inhibits the complement system, potentially shielding tumor cells from immune detection because, unlike in pathogen-bound states, fluid-phase PTX3 may block complement activation." (PMID 39594709, 2024). "This persistent elevation could be attributed to the short 1-week interval between tumor resection and the measurement of serum PTX3 in postoperative patients, which may not have allowed sufficient time for PTX3 to degrade completely in the bloodstream." (PMID 39686456, 2024). "Interestingly, we found that the Tumor 5 (12.9%, range 0-43.7% per PDAC), expressing Pan-Ck, Ck-7 and PTX3 was almost exclusively found in PDAC #1 and #3 only, counting for the 90% of all identified Tumor 5 cells, who were diagnosed with distant metastasis at the time of surgery." (PMID 39575252, 2024). "Finally, the exact role of PTX3 in cancer has not been fully elucidated; however, it was suggested as an oncosuppressor in mice and humans via regulation of complement-dependent tumor-promoting inflammation." (PMID 36868311, 2023). "Therefore, PTX3, under the regulation of DNA methylation, could affect the expression of CCL2 and further regulate pro‐tumour inflammation." (PMID 36872292, 2023). "In accordance with the concept of complement as an enhancer of tumour promotion, no colocalization between PTX3 and terminal C5b-9 was assessed, indicating the possible elimination of C5b-9 from the cancer cell surface or interference with C5b-9 stability to maintain carcinogenesis." (PMID 34572075, 2021). "Accordingly, the pattern recognition receptor Long Pentraxin 3 (PTX3), a secreted/stromal component of innate immunity able to bind and inactivate various members of the FGF family, including FGF2, has revealed potent anti-angiogenic and anti-tumor properties in different FGF-dependent tumors." (PMID 34066669, 2021). "Given that CSCs typically compose only a minor fraction of tumor cells, upregulation of PTX3 in CSCs may not be inconsistent to its weak expression in bulk tumors." (PMID 32427938, 2020). "Preliminary data mining on Gene Expression Omnibus (GEO) database revealed that the expression levels of PTX3 in BC are lower than those found in normal bladders, and decrease along tumor progression from non-muscle invasive lesions (NMIBC)/carcinoma in situ (CIS) to invasive cancer (MIBC)." (PMID 31480336, 2019). "We demonstrate that PTX3 production by tumor cells decreases along the progression from low-grade to high-grade/MIBC, with an oncosuppressive impact on the biological features of BC growth, including tumor cell proliferation, motility, metabolism, stemness, and drug resistance." (PMID 31480336, 2019). "Lack of the functional PTX3 and/or fH might exacerbate pathophysiological consequences during tumor growth and development due to complement dysregulation." (PMID 30619374, 2018). "The anti-angiogenic/anti-tumor activity of PTX3 was not restricted to FGF2." (PMID 30349543, 2018). "Furthermore, the down-regulation of several proangiogenic factors (uPA, PTX-3, and IGFBP-1) known to foster tumor angiogenesis suggests that NX might indirectly prevent angiogenesis by affecting the tumor microenvironment." (PMID 29156770, 2017). "The main sources of PTX3 were permeating through leukocytes and endothelial cells, not tumor cells." (PMID 27377307, 2016). "Interestingly, and in support of the prevalent origin of PTX3 from immune cells, the main source of PTX3 were infiltrating leukocytes and endothelial cells, but not tumor cells." (PMID 26075183, 2015). "Moreover, PTX3, COLEC12 and PDGFRA genes were found as possible candidates for biomarkers of ATC while GPR110 could be tested to distinguish PTC over other tumor subtypes." (PMID 25887408, 2015).
tumor (continued). "Analysis of pro-inflammatory phenotype in tumor samples and in cancer stem cells from GBM was conducted at the mRNA and protein levels by studying the expression of the membrane receptors RAGE and P2X7R, the inducible enzymes COX2 and NOS2, and the acute phase protein PTX3." (PMID 21489226, 2011). "To determine whether the identified stroma-derived secreted factors contributed to STAT6 phosphorylation, we treated mutant desmoid tumor cells with recombinant secreted factors differentially expressed by the nonmutant cells and found that PTX3 induced the highest increase in phospho-STAT6." (PMID 37377751, 2023). "The high expression of PTX3 may be regulated by JNK-Jun, IKK/nuclear factor kappa B (NF-κB), and Wnt signaling pathways, so as to promote the expression of epithelial–mesenchymal transition (EMT)-related proteins and enhance the migration and invasion abilities of tumor cells." (PMID 35982954, 2022). "Moreover, the expression levels of PTX3, TNFAIP6, and TNFAIP8L2 and the genetic alterations of TNFAIP1, TNFAIP6, and STEAP4 greatly impact the clinical outcome of HNC patients, likely by regulating the PI3K-Akt, Ras or other signalling pathways or by regulating tumour immune status." (PMID 34344926, 2021). "Beside the antiangiogenic activity exerted by MM-released PTX3, we cannot rule out the possibility that a direct “autocrine” effect exerted by PTX3 overexpression on MM cells may contribute to the observed inhibition of tumor growth and dissemination." (PMID 34066669, 2021). "The results showed that hGF and PTX3 expression was downregulated and S100P expression was upregulated in LUAD, and that the expression of all the three was correlated with immune cell infiltration, suggesting that all the three gene could promote tumor progression." (PMID 34745947, 2021). "However, no current research has bridged PTX3 and tumor progression through the Fcγ receptor." (PMID 33013829, 2020). "Thus, PTX3 expression affects tumor cells viability by negative regulating cells autophagy." (PMID 32984316, 2020). "Although the direct receptor target of BmK AGAP has not been identified, evidence indicates it downregulates pentraxin-3 (PTX3), a key mediator of receptor–ligand interactions in the tumor microenvironment." (PMID 41155199, 2025). "Although MC38 cells exhibit a very low level of Ptx3 expression, mice bearing MC38 tumors exhibited higher levels of plasma Ptx3 than mice without a tumor burden." (PMID 38243273, 2024). "Another possibility for the lack of difference in PTX3 levels between controls and patients with NMBIC could be due to the absence of tumour invasion into the bladder walls." (PMID 38542446, 2024).
infection (144 papers, 2008 to 2026). The state of being infected such as from the introduction of a foreign agent such as serum, vaccine, antigenic substance or organism. "PTX3-deficient (PTX3 -/-) mice which had resolved a primary infection exhibited enhanced resistance to secondary challenge compared to their wild-type (WT) controls." (PMID 41743710, 2026). "The A allele of these variants is linked to elevated plasma PTX3 levels and increased susceptibility to clinical conditions such as infections caused by P. aeruginosa and A. fumigatus." (PMID 40313930, 2025). "Analysis of the susceptibility of wild-type, PTX3-deficient, complement C3-deficient and Ptx3-/-/C3-/- mice to infection revealed that PTX3 exerts its protective effects against K. pneumoniae in a complement-independent manner." (PMID 40313930, 2025). "When infection caused by fungus, bacteria, and viruses occurs, PTX3 functions as a protective molecule against these infectious agents." (PMID 39594709, 2024). "Collectively, these findings strongly suggest a relationship between the production of IL-1β at sites of infection, the local induction of PTX3, and the underlying genetic variability." (PMID 38790226, 2024). "Serum PTX3 has been identified as a potential predictor of mortality during infection and is known to be associated with TNF-α and IL-1β, which are crucial proinflammatory mediators." (PMID 39666228, 2024). "We then evaluated the phagocytic ability of neutrophils recruited in vivo during the infection comparing WT and Ptx3-deficient mice." (PMID 37222419, 2023). "Previous studies have indicated that Plasma-PTX3 is associated with death and poor outcomes during hospital admissions and infections." (PMID 36862691, 2023). "Our previous studies have identified that the PTX3 protein is involved in the infection of S. suis, though its underlying roles are still not fully understood." (PMID 36977278, 2023). "Given the mild expression of PTX3 during the first hours, we investigated the second phase of neutrophil recruitment, comparing Ptx3-deficient and WT mice 18 hr after infection." (PMID 37222419, 2023). "The supplements of exogenous PTX3 caused significant increases in inflammatory cells in a dose-dependent manner during the infection with SS2 strain HA9801." (PMID 36977278, 2023). "In humans, PTX3 gene polymorphisms were already described to have an impact on the susceptibility to selected infections, induced in particular by Mycobacterium tuberculosis, Pseudomonas aeruginosa and uropathogenic Escherichia coli." (PMID 37222419, 2023). "This association was confirmed 24 hr post-infection, when a strong PTX3 staining was present near the recruitment site of inflammatory cells forming inflammatory foci." (PMID 37222419, 2023). "PTX3 has been considered a biomarker of disease severity in different infections caused by bacteria, fungi, or viruses." (PMID 35676730, 2022). "Previous studies showed that PTX3 deficiency is associated with higher bacterial load, more severe outcome and mortality after infection with A. fumigatus, P. aeruginosa, Escherichia coli and Shigella flexneri." (PMID 34093560, 2021). "In related studies, PTX3-deficiency is highly associated with increased both severity of infection and sensitivity to pathological inflammation." (PMID 33746606, 2021). "In contrast, at the late stage of infection (44 h), PTX3-deficiency was associated with more severe local and systemic infection." (PMID 34093560, 2021). "In this study, taking advantage of PTX3-deficient mice and well-established in vivo models of K. pneumoniae severe infection, we demonstrated the actual protective role of PTX3 in defense against K. pneumoniae." (PMID 34093560, 2021). "The present study was designed to address the role of the long pentraxin PTX3 in innate resistance to K. pneumoniae infection, taking advantage of PTX3-deficient mice and well-established in vivo models of K. pneumoniae severe infection." (PMID 34093560, 2021).
infection (continued). "Taken together, these results highlight the potential role of genetic variation in PTX3 as an important predictor of the risk of infection, but also the outcome of the patients." (PMID 30766534, 2019). "Focusing on the context of infective diseases, PTX3 has been characterized as a biomarker of severity and outcomes in different infections caused by bacteria, fungi or viruses." (PMID 31031772, 2019). "NF-κB target genes (i.e., C3, Chi3l1, Fas, Gadd45β, Hmox1, Ptx3, Saa3, Tlr2) were also abundant in DEGs in which upregulation during infection was impaired by CCR5-deficiency." (PMID 31506064, 2019). "This work allowed the description of the association of PTX3 human genetic polymorphisms with susceptibility to infections with Aspergillus fumigatus in immunocompromised patients and with uropathogenic Escherichia coli." (PMID 29204145, 2017). "Despite the promising role of PTX3 in the risk stratification of various infections and inflammatory conditions, the prognostic relevance in patients with NSTI remains to be evaluated." (PMID 26880104, 2016). "Collectively, our data indicate that PTX3 deficiency delays the development of RRV clinical signs in infected mice during early infection and assists in rapid recovery in the latter stages of disease." (PMID 25695775, 2015). "Ptx3-deficient mice are characterized by a higher susceptibility to infection with selected pathogens, such as Aspergillus fumigatus, Pseudomonas aeruginosa, Salmonella typhymurium and uropathogenic Escherichia coli." (PMID 25786110, 2015). "In context of lung, despite a reported protective effect of PTX3 in infection by certain fungi, bacteria, or viruses, enhanced expression of PTX3 was associated with more severe lung injury." (PMID 26644796, 2015). "Pentraxin 3 (PTX3) was significantly associated with response to infection and increased the expression in both SCC and blood PMN." (PMID 23046560, 2012). "PTX3, another novel CO target, is produced at sites of infection by macrophages and has been implicated in acute lung injury." (PMID 19956541, 2009). "The detection of PTX3 gene polymorphisms thus may help predict the risk of infection by a variety of pathogens and provide insights on disease susceptibility." (PMID 40313930, 2025). "In addition, significant PTX3 expression has also been observed in infections caused by hepatitis B virus, hepatitis C virus and dengue virus infections." (PMID 40313930, 2025). "Furthermore, an animal study has confirmed that PTX3-deficient mice exhibit increased susceptible to infection with laboratory strains of P. aeruginosa." (PMID 40313930, 2025). "In addition, NF-κB target genes (i.e., C3, Chi3l1, Fas, Gadd45β, Hmox1, Ptx3, Saa3, Tlr2) were abundant in the DEGs in which upregulation during infection was impaired by CCR5-deficiency." (PMID 31506064, 2019). "However, this is the first study to look at infection (chronic and thus colonization) versus acute (bacteria-associated) exacerbations demonstrating modest utility of PTX3." (PMID 28458531, 2017). "PTX3 is an essential component of the innate immune response against several pathogens such as fungi and viruses, which often cause severe and even fatal infections in the post-transplant period." (PMID 27893415, 2016). "Furthermore, the effects of PTX3 deficiency on viral entry into primary fibroblasts during the early stages of infection were examined." (PMID 25695775, 2015). "PTX3 is a candidate diagnostic marker of infection and vascular damage." (PMID 23248627, 2012). "Additionally, our study focused on the role of PTX3 in LPS-induced liver injury, but the extent to which PTX3 contributes to defense against other infections, such as those caused by gram-positive bacteria and fungi, remains unclear." (PMID 39666228, 2024).